NAT10 (N-acetyltransferase 10)
Diseases named in the same sentence as NAT10 in open-access papers (continued):
Sharing a sentence is not in itself a finding about the gene and the disease.
tumor (continued). "NAT10 drives metabolic reprogramming via ac4C modification to upregulate glycolytic and lipogenic genes, enhancing biosynthesis and fueling tumor cell proliferation." (PMID 41316475, 2025). "Knockdown of NAT10 restrains cancer cell proliferation and migration in vitro and tumor growth and brain metastasis in vivo." (PMID 40138393, 2025). "Understanding the role of NAT10 in the tumor microenvironment will help facilitate the development of targeted drugs." (PMID 40588654, 2025). "To further verify the necessity of VEGFA in NAT10-mediated angiogenesis and abnormal tumor vascularization, we transfected NAT10-knockdown GC cells with VEGFA expression plasmids." (PMID 40860183, 2025). "Recently, in addition to its effect on mRNA, NAT10-mediated ac4C modification has also been found to play an important role in tumours." (PMID 40169553, 2025). "In summary, we showed that NAT10 in tumor cells drive PNI progression in PDAC by mediating mRNA ac4C modification." (PMID 40119353, 2025). "Therapeutic inhibition of NAT10 with Remodelin normalized tumor vasculature, reduced interstitial pressure, and enhanced CD8+ T-cell infiltration through CXCL9/10/11 upregulation." (PMID 40860183, 2025). "Building upon our prior discovery of the NAT10/SEPT9/HIF-1α positive feedback loop driving glycolytic addiction in GC11, this work unveils a novel NAT10/XIST/YAP1/VEGFA axis governing tumor vascular ecology." (PMID 40860183, 2025). "Emerging evidence suggests that NAT10-mediated ac4C modification regulates mRNA stability and contributes to the development of inflammatory, metabolic, autoimmune, and neoplastic diseases." (PMID 41291301, 2025). "Blocking NAT10-mediated gene-ac4C or decreasing the expression of NAT10 has the potential to alleviate tumor drug resistance or tumor progression." (PMID 41316475, 2025). "Third, while in vivo experiments confirmed tumor growth inhibition, the specific contributions of NAT10/FOXD1 cascade to metastasis or microenvironmental crosstalk remain unexplored." (PMID 40999468, 2025). "In normal tissues, NAT10 is predominantly localized in the nucleolus; however, in tumor cells, it exhibits aberrant expression patterns within the nucleus, cytoplasm, and cell membrane." (PMID 41189569, 2025). "Here, we demonstrate that NAT10 drives pathological angiogenesis and vascular dysfunction in murine tumor models." (PMID 40860183, 2025). "Unresolved questions, such as microbiota-mediated ac4C regulation and NAT10’s impact on the tumor immune microenvironment, highlight future research directions." (PMID 40881352, 2025). "Recent studies have highlighted NAT10’s involvement in pathological conditions, particularly cancer, where its dysregulation promotes tumor proliferation, metastasis, and therapy resistance by stabilizing oncogenic transcripts." (PMID 40588654, 2025). "Another study showed that abnormally overexpressed NAT10 in ESCA is significantly negatively correlated with tumor diameter and overall survival." (PMID 39764566, 2025). "Recent studies reveal that NAT10-catalyzed ac4C epigenetic modification regulates tumor ferroptosis." (PMID 40881352, 2025). "NAT10 exhibits significant translocation changes in tumor cells and is positively correlated with EMT." (PMID 41189569, 2025). "According to the current study, NAT10 plays a crucial role in tumor resistance since its expression was much higher in EGFR-TKI-resistant NSCLC tissues and cells and increased resistance to EGFR-TKIs." (PMID 41310903, 2025). "NAT10 can affect tumor cell proliferation, metastasis, and stress tolerance through its acetyltransferase properties." (PMID 39817252, 2025). "Among them, the NAT10 writing protein is highly expressed in tumor tissues, catalyzing the acetylation of cytosine in various cancer-related RNAs to form ac4C modification and promoting the malignant behavior of tumor cells." (PMID 40606759, 2025).
tumor (continued). "CLIC3 inhibits NAT10 acetylation, reducing ac4C on p21 mRNA; p21 blocks cell cycle, inhibiting tumor proliferation." (PMID 41446042, 2025). "Abnormal expression of NAT10 disrupts the normal function of these adhesion molecules, enhancing the detachment and migration of cancer cells, and ultimately promoting tumor invasion and metastasis." (PMID 39764566, 2025). "On day 28, the mice were euthanized, and subcutaneous tumors were excised and weighed, confirming that NAT10 knockdown led to markedly reduced tumor weights." (PMID 40303290, 2025). "Emerging evidence also implicates aberrant NAT10 expression in tumor immune evasion, although systematic in vivo and in vitro studies on its precise mechanisms remain limited." (PMID 41203621, 2025). "NAT10 induces glycolysis and immunosuppressive tumor microenvironment by upregulating the upstream genes of glycolysis such as FOXP1 and JunB by stimulating ac4C modification of their mRNAs." (PMID 40588654, 2025). "Concurrently, DKC1-mediated Ψ modification and NAT10-catalysed ac4C modification further promote tumor progression by influencing rRNA function and enhancing mRNA stability, respectively." (PMID 41446042, 2025). "The tumor tissues were subsequently investigated using H&E staining and Ki-67 immunohistochemical analysis, which showed that NAT10 knockdown significantly increased the therapeutic efficacy of gefitinib and Osimertinib." (PMID 41310903, 2025). "Further studies are expected to enhance understanding of NAT10's functions and develop more effective intervention strategies in tumor immune therapy." (PMID 39764566, 2025). "In tumor cells, NAT10‐mediated ac4C acetylation can promote glycolysis and lipid metabolism pathways, providing the energy and biosynthetic precursors needed for rapid growth." (PMID 39764566, 2025). "Immunofluorescence analysis also showed that NAT10 was primarily expressed in tumor cells in human PDAC tissues." (PMID 40119353, 2025). "Here, we expand the current understanding of RNA chemical modification in cancer neuroscience by demonstrating that NAT10 expression in tumor cells promotes the progression of PNI and metastatic phenotypes in PDAC." (PMID 40119353, 2025). "The results of subcutaneous xenograft and caudal vein injection showed that NAT10 promoted tumour growth and metastasis in vivo, while Remodelin inhibited tumour growth." (PMID 40169553, 2025). "This study presents a novel potential research target for the pathogenesis of ccRCC and provides a new perspective for exploring the tumor-promoting mechanism of NAT10." (PMID 41189569, 2025). "At the end point (day 58), the tumor size and weight in the NAT10 knockdown group were significantly reduced compared to the control tumors." (PMID 40138393, 2025). "NAT10, frequently upregulated in various tumors, mediates mRNA ac4C modification and plays a vital role in tumor proliferation, drug resistance, DNA damage repair, and cell metabolism, making it a promising target for anticancer therapy." (PMID 41446042, 2025). "Given the crucial role of PNI in tumor dissemination and its close association with poor prognosis in patients with PDAC, we next investigated the effect of stable NAT10 KD on the PNI ability of PDAC cells." (PMID 40119353, 2025). "In summary, NAT10-driven ac4C modification constitutes a complex regulatory network that coordinates tumor cell invasion, metabolism, and proliferation." (PMID 41446042, 2025). "The tumor microenvironment undergoes NAT10-driven remodeling through metabolic and immune modulation." (PMID 40588654, 2025). "In ESCC cells, the most potent inhibition of tumor growth was achieved with the combination of NAT10 silencing and PD-1 blockade." (PMID 41316475, 2025). "As expected, the Ki-67 level in the HB tumor tissues of nude mice treated with Remodelin was significantly reduced, suggesting that the NAT10 inhibitor has good therapeutic potential in vivo." (PMID 40303290, 2025).
tumor (continued). "SMAD3 overexpression fully rescued the tumorigenic capacity of NAT10‐knockdown cells in the mouse xenograft model, with a marked increase in both tumor volume and weight in the SMAD3‐rescue group." (PMID 41476650, 2025). "Remodelin (Rem), a small-molecule inhibitor of NAT10, has been reported to inhibit tumor progression." (PMID 40119353, 2025). "Recently, it has also been shown that NAT10-mediated mRNA ac4C modification plays an important role in tumour development." (PMID 40169553, 2025). "Owing to its high expression in malignant tumors, NAT10 represents a promising target for tumor treatment." (PMID 41316475, 2025). "In subsequent trials, the authors established the tumor-bearing rat model to explore the role of kynurenine and NAT10 in vivo." (PMID 40245789, 2025). "Given the growing recognition of RNA ac4C's role in tumor biology, several NAT10‐targeted drugs have been identified, such as Remodelin, paliperidone, and AG‐401." (PMID 41476650, 2025). "NAT10 has been shown to increase tubulin protein stability through acetylation, which in turn impacts tumor invasion and metastasis." (PMID 39817252, 2025). "NAT10 promotes tumor cell invasion and metastasis by inducing EMT, but the molecules and pathways involved are not well understood due to limited research and require further exploration." (PMID 41189569, 2025). "In the TCGA_GBM datasets, NAT10 mRNA expression was significantly increased in GBM tissues compared to non-tumor brain regions." (PMID 40288646, 2025). "In PC, NAT10 promotes tumor metastasis via ac4C-mediated modifications on receptor tyrosine kinases." (PMID 41203621, 2025). "In contrast, chloride intracellular channel 3 (CLIC3) inhibits tumor proliferation by inhibiting NAT10 acetylation and reducing the ac4C level on p21 mRNA, revealing an internal balance mechanism within this pathway." (PMID 41446042, 2025). "Immunofluorescence staining revealed that NAT10 staining was strongly positive in a large fraction of cytokeratin 19 (CK19) + tumor cells." (PMID 40119353, 2025). "Taken together, these results demonstrated that emodin inhibited tumor growth as well as NAT10 and PGK1 expression in vivo." (PMID 41426311, 2025). "In vivo, NAT10 knockdown significantly inhibited tumor growth, enhanced CD8 + T cell infiltration, and reduced lung metastasis." (PMID 41203621, 2025). "Further research revealed that NAT10 facilitates tumor progression and lymphangiogenesis in ccRCC by promoting the nuclear entry of the Yes1‐associated transcriptional regulator." (PMID 39764566, 2025). "Mice-bearing NAT10 KO U251 cells exhibited significantly prolonged survival and reduced tumor growth compared to those bearing naive U251 cells." (PMID 40288646, 2025). "Remarkably, the combination of olaparib and remodelin, an inhibitor of NAT10, induced robust anti-tumor effects in vitro and in vivo by promoting DSBs." (PMID 40606759, 2025). "This indicated that NAT10 expression was significantly increased in HB tumor tissues and cell lines." (PMID 40303290, 2025). "Emerging evidence establishes NAT10 as a pivotal regulator of the tumor immune microenvironment, where it fosters an immunosuppressive niche by modulating the expression of key immunoregulatory molecules in cancer cells." (PMID 41316475, 2025). "With the catalysis of NAT10, ac4C modification participates in tumor initiation, drug resistance, and development." (PMID 40301349, 2025). "These targets reportedly play important roles in a variety of tumor types and displayed significantly decreased expression patterns following NAT10 knockdown." (PMID 39817252, 2025). "Research on the relevant molecular mechanism by which NAT10 regulates ferroptosis revealed that NAT10 affected ferroptosis, which is closely related to tumor cells, by influencing the key regulatory molecules GPX4 and NFE2L1 of ferroptosis." (PMID 41189569, 2025).
tumor (continued). "Combining NAT10 inhibition with direct targeting of the CD2BP2‐DT/YBX1 signaling pathway provides a multifaceted strategy to suppress tumor cell proliferation and survival, thereby potentially enhancing therapeutic efficacy." (PMID 39976088, 2025). "In OSCC, we found that NAT10 is highly expressed and significantly correlated with tumor immune infiltration." (PMID 40597017, 2025). "The circMAST1 selectively binds to NAT10, inhibiting the ac4C modification of Yes-associated protein (YAP) mRNA, thereby promoting its degradation and impeding tumor development in CCa." (PMID 39969189, 2025). "As the only RNA N4-acetylcytidine (ac4C) modifying enzyme discovered so far, N-acetyltransferase 10 (NAT10) has been widely studied in both tumor and non-tumor diseases." (PMID 40606759, 2025). "The results indicated that in tumor tissues with NAT10 overexpression and G6PD knockdown, the G6PD and Ki-67 expression were significantly lower." (PMID 40303290, 2025). "NAT10, as a critical epitranscriptional regulatory factor, has garnered significant attention in recent years for its role in tumor prognosis assessment." (PMID 39764566, 2025). "Compared with monotherapy or control, combination therapy with an NAT10 inhibitor and an anti-PD-L1 antibody significantly inhibited tumor growth." (PMID 41203621, 2025). "In vivo, the results of subcutaneous tumour formation and caudal vein metastasis in mice showed that knockdown of NAT10 inhibited tumour growth and metastasis and that intraperitoneal injection of Remodelin effectively inhibited tumour growth." (PMID 40169553, 2025). "Collectively, these findings demonstrate that PNS effectively counteracts UVB-induced suppression of the acetyltransferase NAT10, supporting its potential involvement in maintaining NAT10-mediated molecular functions during UVB-induced skin sunburn injury." (PMID 41408569, 2025). "NAT10 is acknowledged as the only “writer” protein for ac4C and is essential in the processes of tumor metastasis and tumorigenesis." (PMID 41316475, 2025). "Remodelin, the NAT10's inhibitor, inhibited the tumor growth by downregulating the ac4C acetylation of downstream functional genes via suppressing the expression of NAT10 in multiple cancers." (PMID 39640362, 2024). "NAT10‐mediated ac4C modification influences the tumor microenvironment and immune cell function in HCC." (PMID 39640362, 2024). "This study demonstrates a link between tumor lactate metabolism and the immune microenvironment via NAT10‐mediated ac4C modification." (PMID 39640362, 2024). "NAT10 is also delivered to macrophages in the tumor microenvironment via exosomal packaging, promoting macrophage M2‐type polarization and biasing lipid metabolism, further supporting immune escape from tumors." (PMID 39640362, 2024). "Our results showed that tumor volumes and weights of cancer tissue were significantly decreased in mice inoculated with lentiviral stable NAT10 knockdown cells as compared with those derived from empty lentivirus transfected, supporting the previous findings." (PMID 38233839, 2024). "The specific mechanism of ac4C modification in RNA catalyzed by NAT10 to participate in tumor development is still unclear." (PMID 38233930, 2024). "Mechanistically, circMAST1 competitively sequestered N-acetyltransferase 10 (NAT10) and hindered Yes-associated protein (YAP) mRNA ac4C modification to promote its degradation and inhibit tumor progression in CCa." (PMID 38331765, 2024). "As a novel RNA modification, ac4C acetylation presents significant therapeutic potential, positioning NAT10 as a promising target for the treatment of multiple tumor types." (PMID 39640362, 2024). "The participation of NAT10 in tumorigenesis and tumor progression is well-documented, and its role in drug resistance is increasingly recognized." (PMID 39246323, 2024).
tumor (continued). "NAT10 can enhance tumor cell proliferation by regulating the cell cycle, leading to G1/M phase arrest, and can facilitate tumor invasion, migration, and metastasis by suppressing apoptosis and promoting EMT." (PMID 39640362, 2024). "To investigate the role of NAT10 in regulating tumor proliferation and metastasis in vivo, we performed subcutaneous tumor xenograft in male BALB/c nude mice." (PMID 38922788, 2024). "NAT10 knockdown significantly impaired CD8+ T cell cytotoxicity at a 1:1 tumor-to-CD8+ T cell ratio." (PMID 39648231, 2024). "Analysis of tumor weight and volume trends demonstrated that NAT10 knockdown significantly inhibited tumor growth, with Remodelin exhibiting a similar effect comparable to shNAT10." (PMID 38826095, 2024). "Our in vivo experiments revealed that knockdown of NAT10 drastically suppressed tumor growth and increased the infiltration and activity of CD8+ T cells." (PMID 38243170, 2024). "NAT10 enhances programmed cell death‐ligand 1 (PD‐L1) expression by acetylating nucleophosmin 1, which allows tumor cells to evade immune surveillance more effectively." (PMID 39640362, 2024). "The GSEA highlighted NAT10's capacity to influence the PCa tumor microenvironment, specifically via the Wnt and TGF-β signaling pathways, consistent with previous findings." (PMID 39648231, 2024). "This group discovered that NAT10 is involved in the clinical outcome of the disease and tumor tissue infiltration, drug resistance, migration, and clonogenic potential." (PMID 38233930, 2024). "The tumor volumes of mice with stably transfected NAT10 knockout cells were reduced by 57.1% and the tumor tissue weight was only 0.20 times that of the empty lentivirus transfected." (PMID 38233839, 2024). "Normal tissue cells express NAT10 in the nucleus, whereas tumor cells translocate NAT10 to the cytoplasm, and this affects tumor formation." (PMID 38169284, 2024). "Further manipulating of NAT10 gene expression in MM cells shows that enforced NAT10 expression decreases sensitivity to PI, however knockdown of NAT10 enhances anti-tumor efficacy of PIs in MM cells in vitro and in vivo." (PMID 39513105, 2024). "The impact of NAT10 on tumor cell proliferation, migration, and invasion was investigated via in vitro assays—including CCK-8, EdU, wound healing, and 3D-Transwell—as well as in vivo mouse xenograft models and organoid studies." (PMID 39648231, 2024). "In order to confirm the role of NAT10 in modulating the tumor microenvironment in vivo, stable NAT10 knockdown MC38 cells were generated." (PMID 38243170, 2024). "Activation of the NAT10/FOXP1 axis in CC cells inhibits immune response by modulating glycolysis in tumor cells." (PMID 39640362, 2024). "YTHDC1 partially abrogated the inhibitory effect caused by NAT10 knockdown in tumor models in vivo, lentiviral overexpression of YTHDC1 partially restored the reduced stability of YTHDC1 caused by lentiviral depleting NAT10 at the cellular level." (PMID 38233839, 2024). "The present review thoroughly analyzes the current knowledge on NAT10‐mediated ac4C modification in cancer, highlighting its broad regulatory influence on targeted gene expression and tumor biology." (PMID 39640362, 2024). "Despite its crucial biological function, NAT10 has also been reported to promote tumor development in various cancers." (PMID 38233839, 2024). "NAT10 is recognized as an oncogene, with alterations in its expression and localization observed in malignant tumour cells." (PMID 39482983, 2024). "It was found that the expression of Ki‐67 proliferation antigen and HMGA1 was significantly weaker in the NAT10 knockdown tumor tissues compared with the control group." (PMID 38922788, 2024). "This study aimed to investigate the correlation between NAT10 expression and PCa cell malignancy, along with elucidating NAT10’s role in the tumor microenvironment." (PMID 39648231, 2024).